TMPRSS2 (transmembrane serine protease 2)
Diseases named in the same sentence as TMPRSS2 in open-access papers (continued):
Sharing a sentence is not in itself a finding about the gene and the disease.
COVID-19 (continued). "It has also been reported that COVID-19 may have a direct cytotoxic effect on b-cells by binding to the angiotensin converting enzyme 2 (ACE2) receptor or by proteolytic cleavage of the viral spike protein by the serine transmembrane protease 2 (TMPRSS2)." (PMID 35784550, 2022). "Thus, targeting the metalloproteinase pathway in addition to the TMPRSS2 and endosomal pathways could be an effective strategy by which to cure COVID-19 in the future." (PMID 35708281, 2022). "Because ACE2 is present in tetraspanin-enriched microdomains, where it clusters with other glycoproteins, such as CD9, CD81, and TMPRSS2, we also established assays to define whether anti-IgM antibodies against any of these proteins were present in COVID-19 sera." (PMID 35349483, 2022). "Finally, since TMPRSS2 expression is controlled by androgens, which could explain the greater frequency of severe COVID-19 in males, it is possible that androgen receptor antagonists might reduce susceptibility to developing a serious COVID-19 infection." (PMID 36304162, 2022). "Current evidence showed that COPD subjects have increased pulmonary expression of angiotensin-converting enzyme 2 (ACE2) and transmembrane serine protease 2 (TMPRSS2) in lung tissues, which may predispose patients to an increased risk of worse outcomes from COVID-19." (PMID 36560586, 2022). "However, the T allele in TMPRSS2 had no protective effect against development of severe COVID-19 symptoms." (PMID 36532428, 2022). "Considering that a low expression of TMPRSS2 is significantly associated with a short overall survival in LUAD, low TMPRSS2 expression may result in severity and death of LUAD cancer patients infected with COVID-19 or SARS-CoV-2." (PMID 36364238, 2022). "Whilst its primary mechanism of action is proposed to be inhibition of TMPRSS2 and subsequent viral entry, data in this study suggest that nafamostat has additional immunological effects, which may be beneficial in the treatment of COVID-19." (PMID 34991643, 2022). "Therefore, targeting ACE2 and/or TMPRSS2 to block initial viral entry into the cells could serve as an important therapeutic strategy for COVID-19." (PMID 36187008, 2022). "The TMPRSS2 rs75603675 C/C or C/A genotypes compared with A/A, males compared with females, the presence of dyslipidemia, and a higher CCI score were associated with more severe COVID-19, at the first hospital visit and at the most severe point of disease progression." (PMID 35636966, 2022). "Thus, genetic variants influencing the function of TMPRSS2 and IFITM3 may be expected to contribute to the expression of severe symptoms of COVID-19, or may convey the protective effect." (PMID 35949487, 2022). "Moreover, TMPRSS2 could be a viable drug target in COVID-19 patients, and camostat mesilate, or other novel TMPRSS2 inhibitors, may have a role in the treatment of COVID-19." (PMID 35104687, 2022). "However, the findings of the present study might develop new ideas about how to use TMPRSS2 rs12329760 SNP as a predictor or biomarker of COVID-19 severity or clinical results." (PMID 36457338, 2022). "Similarly, only weak concordant ACE2 or TMPRSS2 expression was found in extra- and intraocular tissues, which may explain the overall rare ocular involvement in COVID-19 patients." (PMID 34580409, 2021). "Therefore, the increased (co-)expression of ACE2 and TMPRSS2 in SARS-CoV-2 target tissues may explain the higher occurrence of COVID-19 complications in males." (PMID 34925228, 2021). "Hence, differential tissue expression of ACE2 and TMPRSS2 might link viral injury to organ systems and may explain the observed correlation between high respiratory and plasma viral loads and severe COVID-19 and mortality." (PMID 33828231, 2021). "However, similar TMPRSS2 expression levels in males and females were observed in lung tissues from mice and humans, which challenges the decisive role of TMPRSS2 in gender differences in COVID-19 outcomes." (PMID 34001144, 2021).
COVID-19 (continued). "Therefore, we investigated whether risk for AKI in COVID-19 is associated with urinary SARS-CoV-2 N, ACE2, and TMPRSS2 levels, thus allowing for simple and fast identification of patients at risk." (PMID 34113632, 2021). "TMPRSS2 contains a trypsin-like extracellular catalytic domain, and therefore, the salt bridging feature may help screen and repurpose existing drugs against TMPRSS2 for COVID-19 treatment." (PMID 34209110, 2021). "Notably, differences in ACE2 and TMPRSS2 expression levels in the lower airway might contribute to COVID-19 severity." (PMID 33981629, 2021). "Moreover, knowing that age and gender may determine risk for increased COVID-19 severity, we have also determined whether ACE2 and TMPRSS2 lung tissue expression levels differs relative to age and gender of asthmatic patients." (PMID 35111161, 2021). "Therapeutic inhibition of the TMPRSS2 and furin may be used as a therapeutic approach for COVID-19." (PMID 34527703, 2021). "Furthermore, our data may also support the idea of targeting TMPRSS2 in COVID-19 therapy, as has been done in some clinical trials." (PMID 34001248, 2021). "Furthermore, ACE2 and TMPRSS2 genetic variants are not convincingly associated with COVID-19 severity." (PMID 33828231, 2021). "Finally, the expression level of NRP1 and TMPRSS2 in COVID-19 patients was analyzed using the public datasets: NRP1 is decreased in peripheral blood of COVID-19 patients admitted to intensive care unit (ICU), but the level of NRP1 in the lung of COVID-19 patients is not changed." (PMID 34168096, 2021). "The transcription of TMPRSS2 is promoted by androgen receptors, which could explain the predominance and the severity of pathological signs in COVID-19-affected men compared with women, the higher proportion of men's hospitalization and their higher mortality rates." (PMID 33996744, 2021). "Therefore, androgen-AR-mediated mechanisms could explain sex-specific differences in COVID-19 outcomes by TMPRSS2-independent mechanisms." (PMID 34045511, 2021). "In addition to the androgen, nicotine smoking increases the expression of the TMPRSS2 gene, which might explain the severity of COVID-19 severity in nicotine smoker patients." (PMID 34568081, 2021). "Transmembrane protease serine 2 (TMPRSS2), an androgen-induced protease associated with prostate cancer, is one putative receptor for coronavirus entry into host cells, where triggering aggressive inflammatory cytokine storm and possibly death in COVID-19 patients." (PMID 33791688, 2021). "The expression of TMPRSS2, the co-factor of ACE2, was also significantly higher in lung cancer patients than in the general population (Wilcoxon’s rank-sum test, P < 0.001), suggesting that patients with lung cancer were more likely to be susceptible to COVID-19." (PMID 34094930, 2021). "In particular, the high levels of JARID1B, ACE-2, and TMPRSS2 expression in respiratory epithelial cells indicate that further research could improve our understanding of the pathogenesis of viral infections such as COVID-19." (PMID 34445368, 2021). "As SARS-CoV-2 cellular entry depends on the ACE2 receptor and TMPRSS2 priming of the spike protein, it is important to understand the molecular mechanisms through which these two proteins and their cognate transcripts interact and influence the pathogenesis of COVID-19." (PMID 34834564, 2021). "We only investigated ACE2 and TMPRSS2 expression in the lung and circulating levels of ACE2 in the plasma, and it may be that expression in other tissues is more relevant to the risk and severity of COVID-19." (PMID 33391794, 2020). "Taken together, these observations suggest that a subgroup of individuals may be exceedingly susceptible to developing severe COVID-19 due to concomitant high preexisting ACE2 and TMPRSS2 expression and low baseline levels of CD8+ T cells and NK cells in the lung." (PMID 32873611, 2020).
COVID-19 (continued). "Our data are significant in the clinical scenario; indeed, since TMPRSS2 is known to play a crucial role in the pathophysiology of COVID-19, our results could open the field to new research in order to verify the role of miR-98-5p in other tissues and cell types." (PMID 33143053, 2020). "However, it is currently unclear under which conditions the fusion protein is generated, whether TMPRSS2 is also regulated by estrogen, and whether it plays a role in COVID-19." (PMID 32450906, 2020). "Indeed, targeting TMPRSS2 expression and/or activity could be a promising candidate for potential interventions against COVID-19." (PMID 32849840, 2020). "Type 2 transmembrane serine protease (TMPRSS2) is a new member of the serine proteases, and studies have shown that TMPRSS2 plays a role in the occurrence of prostate malignancies and is closely related to the occurrence of the coronavirus disease 2019 (COVID-19)." (PMID 33193689, 2020). "An analysis of the pharmacology of HCQ in COVID-19 reveals certain possible reasons for this failure—a pharmacokinetic failure due to failure to achieve adequate drug concentration at the target site and attenuation of its inhibitory effect due to the presence of TMPRSS2 in airway epithelial cells." (PMID 33390974, 2020). "Thus, TMPRSS2 has been identified as a promising target for treatment of COVID-19." (PMID 32629804, 2020). "The TMPRSS2 inhibitors camostat mesylate, nafamostat, and bromhexine may treat COVID-19." (PMID 32629804, 2020). "Our results parallel the findings from recent studies that revealed the co-expression of ACE2 and TMPRSS2 in olfactory epithelium and intrahepatic cholangiocytes, which may explain atypical COVID-19 symptoms and laboratory findings such as anosmia/dysgeusia and transaminitis." (PMID 32545271, 2020). "As TMPRSS2 transcription is activated upon AR binding, elevated TMPRSS2 in men and individuals with high androgen levels may contribute to sex-based disparities in COVID-19 severity through the following mechanisms: viral replication promotion and humoral immunity suppression." (PMID 32983176, 2020). "One factor that may underlie variation in clinical outcomes of COVID-19 is the extent of gene expression in the airway of the SARS-CoV-2 entry receptor, ACE2, and TMPRSS2, the host protease that cleaves the viral spike protein and thus allows for efficient virus-receptor binding." (PMID 33046696, 2020). "Importantly, we find that targeting the transcriptional regulation of ACE2 and TMPRSS2 may be an attractive treatment approach for COVID-19." (PMID 33310900, 2020). "Analyses of single-cell RNA sequencing data show that co-expression of ACE2 and TMPRSS2 is elevated in absorptive enterocytes from the inflamed ileal tissues of Crohn disease patients compared to uninflamed tissues, revealing shared pathobiology between COVID-19 and inflammatory bowel disease." (PMID 33156843, 2020). "The search strategy keywords were COVID-19, SARS-CoV-2, ACE2, TMPRSS2, protein, level or concentration, age-aging, female-male, and filters ‘human’." (PMID 40631549, 2025). "In contrast, no common KEGG terms were found in downregulated DEGs between TMPRSS2 transfectants of MCF-7 and EA.Hy926 and PBMNCs of COVID-19 patients." (PMID 40055791, 2025). "Therefore, we evaluated whether ACE1, ACE2, and TMPRSS2 gene expression and ACE1 polymorphism (Alu 287 bp) would contribute to the need for mechanical ventilation and chance of death in a cohort of hospitalized COVID-19 patients in Brazil." (PMID 39850833, 2025). "The epipharynx plays a pivotal role in COVID-19 due to the high expression of viral entry factors—angiotensin-converting enzyme 2 (ACE2) and transmembrane protease serine 2 (TMPRSS2)—in the epipharyngeal epithelium." (PMID 40074801, 2025). "Therapies for COVID-19 include use of human recombinant soluble ACE2 to act as decoy receptors for binding and neutralizing SARS-CoV-2 and inhibition TMPRSS2 activity to prevent spike protein priming." (PMID 41007801, 2025).
COVID-19 (continued). "Therefore, reduced TMPRSS2 but increased ACE2 in response to chronic exposure (60 h) to genistein in inflamed Caco-2/TC7 cells could be considered beneficial in attenuating the risk of SARS-CoV-2 infection and COVID-19 pathophysiology." (PMID 40227199, 2025). "In COVID-19, the coronavirus enters cells by binding to the host cell receptor angiotensin-converting enzyme 2 (ACE2) and the cellular serine protease TMPRSS2, triggering immune system activation, and an inflammatory response." (PMID 40612799, 2025). "The main target of the different COVID-19 strains is the angiotensin-converting enzyme 2 (ACE2) receptor and its co-receptor, transmembrane protease, serine 2 (TMPRSS2)." (PMID 39940645, 2025). "Correlation plots between TMPRSS2 and commonly upregulated genes were representively shown for OAS1, STAT1 and IRF7 from COVID-19 vs. healthy PBMNCs." (PMID 40055791, 2025). "Our findings confirm previous studies showing higher expressions of TMPRSS2, ADAM-17, and IL-17A in healthy individuals compared to COVID-19 patients, recovered, and vaccinated individuals." (PMID 40003732, 2025). "Examining autopsy tissues of COVID-19 patients, it becomes evident that there is a notable upregulation of ACE2 expression, along with the presence of TMPRSS2 and the consequential endotheliitis in capillaries." (PMID 39858469, 2025). "Furthermore, our results provide mechanistic evidence suggesting that genistein may be utilised as a preventive measure against the inflammation-induced rise in SGLT1 and TMPRSS2, potentially aiding in lowering postprandial glycaemic response and COVID-19 pathophysiology." (PMID 40227199, 2025). "COVID-19 enters host cells to initiate immunity through the binding of angiotensin-converting enzyme 2 (ACE2) or transmembrane protease, serine 2 (TMPRSS2)." (PMID 39247915, 2024). "Using the TN-cyclonTM, we succeeded in demonstrating that the soluble portion of ACE2, which was removed from 17β-estradiol-treated VeroE6/TMPRSS2 cells, bound to the spike proteins of SARS-CoV-2, thereby reducing COVID-19 infectivity." (PMID 39687610, 2024). "Specifically, two protein targets of COVID-19, ACE2 and TMPRSS2, are embedded in lipid rafts and can actively participate in viral infection." (PMID 38540716, 2024). "The hypothesis that this could be the cause of hypo/anosmia derived from COVID-19 has been questioned by numerous studies that have highlighted the absence of angiotensin-converting enzyme 2 (ACE2) and transmembrane serine protease 2 (TMPRSS2), the key factors for the virus’s entry into the cell." (PMID 38396398, 2024). "Our results showed that in the non-COVID-19 and COVID-19 autopsy, ACE2 and TMPRSS2 were both abundantly expressed in taste buds, serous acini, and salivary gland ducts, where the viral antigens were also primarily located." (PMID 38975331, 2024). "In the context of COVID-19, angiotensin-converting enzyme 2 (ACE2), the main viral receptor, and type 2 transmembrane serine protease (TMPRSS2), the viral entry facilitator, appeared to be regulated by sex steroids." (PMID 39066223, 2024). "As angiotensin converting enzyme 2 (ACE2) and transmembrane protease serine S1 member 2 (TMPRSS2) played crucial roles in viral entry into the human host cells, we therefore investigated in the MHD patients whether their plasma levels were associated with susceptibility to the COVID-19." (PMID 39540040, 2024). "COVID-19 enters the host cell through the binding of its spike protein to ACE2, and this process is facilitated by TMPRSS2 of the host, which cleaves the spike protein into S1 and S2 fragments, thereby enabling cell membrane fusion." (PMID 39057037, 2024). "Correlation between inflammatory cytokines and TMPRSS2 and ACE2 SNPs in healthy controls and COVID-19 patients." (PMID 38855114, 2024). "The spike protein of COVID-19 recognizes the cell surface receptor ACE2 and is reliant on binding to it to enable membrane fusion, with TMPRSS2 acting to prime the spike protein." (PMID 38576426, 2024).
COVID-19 (continued). "More molecular docking studies have shown that luteolin exhibits binding affinity for ACE2 receptor and transmembrane protease serine 2 (TMPRSS2), along with Mpro and RdRp, in COVID-19." (PMID 39126050, 2024). "Hindering viral attachment offers an effective early strategy to combat COVID-19, by targeting miRNAs regulating proteins such as ACE2 and TMPRSS2 important for viral entry into host cells." (PMID 39434774, 2024). "The interaction between TMPRSS2 and TMPRSS4 in the context of COVID-19 suggests a synergistic effect on cancer development, possibly through enhancing the ability of cancer cells to invade and metastasize." (PMID 39350850, 2024). "The entry of COVID-19 into epithelial cells requires the angiotensin-converting enzyme 2 (ACE2) and transmembrane serine protease 2 (TMPRSS2)." (PMID 39597953, 2024). "These compounds were evaluated to determine their potential ligand binding affinity toward established anti-DM and COVID-19 targets, specifically α-glucosidase, α-amylase, ACE2, and TMPRSS2." (PMID 38132859, 2023). "ACE-2 and TMPRSS2 are expressed on the ENS in submucosal and myenteric plexus that can function as a target for COVID-19 invasion and GI damage." (PMID 36979225, 2023). "It remains to be demonstrated that increased TMPRSS2 expression supports enhanced SARS-CoV-2 activation and, as a consequence, a more severe COVID-19 outcome." (PMID 37208193, 2023). "All three human host receptors (ACE2, TMPRSS2, and FURIN) involved in COVID-19 entry are variably expressed in liver tissues." (PMID 36674607, 2023). "Distribution of ACE-1 (rs4343), TMPRSS2 (rs12329760) and ACE-2 (rs908004) SNPs Genotypes among COVID-19 positive patients and healthy controls." (PMID 37426824, 2023). "LLT1 protein can be also detected not only in supernatants of SARS-CoV-2 infected A549ACE2/TMPRSS2 cells and HAE basolateral medium, but also in serum of COVID-19 patients." (PMID 37287972, 2023). "ACE-2 and TMPRSS2 play crucial and synergistic roles in the membrane fusion and viral entry of SARS-CoV-2 (COVID-19)." (PMID 37809955, 2023). "Thus, inhibitors of TMPRSS2 may be a potential treatment for COVID-19." (PMID 37009799, 2023). "This trial study on androgen receptor antagonists which is a novel therapeutic target in COVID-19, inhibiting SARS-CoV-2 infection by regulating ACE2 and TMPRSS2." (PMID 37322522, 2023). "By modulating the expression levels of ACE2 and TMPRSS2, we can effectively inhibit SARS-CoV-2 infection, thereby contributing to the prevention and treatment of COVID-19." (PMID 37894745, 2023). "Here we focus on TMPRSS2, and related genes ACE2, MX1, AR, ETV5 and ERG, by its own or combined with clinical data, as an easy and relevant classifier of COVID-19 aggressiveness." (PMID 37287057, 2023). "In summary, the pathogenesis of COVID-19 unfolds as a multifaceted interplay between SARS-CoV-2 and host receptors, primarily ACE2 and TMPRSS2." (PMID 37893162, 2023). "Even though numerous studieshave assessed the effects of COVID-19 on the brain, very little information is availableconcerning the distribution of ACE2R and TMPRSS2 in the human brain, with particularregard to their topographical expression in the brainstem." (PMID 37172190, 2023). "The expression on proximal tubular renal cells of the key players in cellular viral uptake, ACE2, TMPRSS2, and NRP1, seems to be the mechanism for the direct kidney injury seen in patients with COVID-19." (PMID 38255667, 2023). "COVID-19 uses ACE2, cathepsins, endosomal cysteine ​​proteases, and the ligand Type 2 transmembrane serine protease (TMPRSS2), to enter cells." (PMID 36860224, 2023). "The interest of the researchers toward the possible influences of COVID-19 on male fertility arises from the evidence that testis express ACE2 and TMPRSS2, including spermatogonia, peritubular myoid cells, testis somatic cells, and spermatogonial stem cells." (PMID 36836943, 2023).